IL6 (interleukin 6)
Diseases named in the same sentence as IL6 in open-access papers (continued):
Sharing a sentence is not in itself a finding about the gene and the disease.
Sepsis (continued). "However, our experiments demonstrated that the levels of IL-6 and TNF-α in serum and peritoneum, and cytosolic IL-1β and IL-10 expression in macrophages were similar between WT and Nod2−/− mice during sepsis." (PMID 23675299, 2013). "We observed that PD decreased notably sepsis-induced serum TNF-α and IL-6 levels." (PMID 23431240, 2013). "For example, in one study, serum IL-6 levels at presentation were 796 pg/mL (range: 165 to 83,743) in non-survivors of sepsis." (PMID 24265742, 2013). "IL-6 has the best discriminative power in sepsis and non-infectious SIRS, with sensitivity above 80% and specificity above 70%, which is higher than conventional inflammatory markers including CRP and TNF-α." (PMID 24341820, 2013). "In contrast to TNF-α and IL-1, the injection of IL-6 by itself does not produce a sepsis-like state." (PMID 23853427, 2013). "Indeed cf-DNA was shown to have better discriminatory power than IL-6, thrombin or protein C to predict ICU mortality in sepsis." (PMID 23939536, 2013). "Release of cytokines (IL1β, IL-6, and TNFα), nitric oxide, endotoxins, and activation of caspases (caspases 3) in setting of a gram negative bacteremia and sepsis leading to myocardial depression and ventricular dilatation is another theory to explain SRTE." (PMID 23691359, 2013). "Therefore, in the present study, we sought to examine the role of intra-alveolar IL-6 in the pathogenesis of AKI-mediated lung injury and, for comparison, sepsis (IP endotoxin) and direct lung injury (IT endotoxin)." (PMID 23667439, 2013). "Results from the current study showed that F.n. infected galectin-3−/− animals exhibited a reduction in the levels of sepsis mediators such as vascular injury markers thrombopoietin, fibrinogen, as well as acute phase protein CRP and inflammatory cytokines such as TNF-α, IL-6 and IL-1." (PMID 23527230, 2013). "It has been recently found that dexmedetomidine reduces systemic levels of interleukin- 6 (IL-6), tumor necrosis factor α (TNF-α) and high mobility group box 1 (HMGB1) following lipopolysaccharide infusion or sepsis in animals, indicating its anti-inflammatory effects against renal I/R injury." (PMID 23759023, 2013). "ATF3 presents in the early stage (3 hrs) of endotoxemia to prevent macrophage activation and inhibit NO, IL-6, and TNF-α release that eventually will trigger an uncontrolled systemic inflammatory response that may lead to sepsis." (PMID 24062788, 2013). "Proinflammatory cytokines IL-6 and TNF-α in BALF also decreased after blockade of IL-17A intraperitoneally, indicated that anti-IL-17A antibody treatment suppressed proinflammatory response in sepsis induced lung injury." (PMID 23056325, 2012). "IL-6 and CRP values were significantly higher during the sepsis attacks." (PMID 22672862, 2012). "Inhibitory effect of compound 6e on IL-6 and TNF-α secretion in an animal model of sepsis." (PMID 22664467, 2012). "We showed a higher serum level of PCT, hs-CRP, and IL-6 in neonates with sepsis compared to those without sepsis." (PMID 22708043, 2012). "The correlation coefficients between studied variables in the different groups are as follows: serum levels of PCT were significantly correlated with serum levels of IL-6 in patients with no sepsis (r=0.52, p < 0.05) and uncertain sepsis (r=0.34, p<0.05)." (PMID 22708043, 2012). "IL-6 and TNF-α appeared to be good markers for predicting severity and prognosis of sepsis." (PMID 22731930, 2012). "Plasma IFN-γ, IL6 and IL10 were all significantly increased in patients with sepsis." (PMID 21731667, 2011). "In contrast, plasma IL-6 levels were increased after HVt ventilation compared to sepsis alone but not to LVt with PEEP." (PMID 22204611, 2011). "Herein, we did not further explore the well described anti-inflammatory effects of dexmedetomidine (beyond HMGB1 levels); however, dexmedetomidine reduces systemic levels of IL-6 and TNF-α following lipopolysaccharide infusion in rats and following cardiac surgery and sepsis in humans." (PMID 21702944, 2011).
Sepsis (continued). "Median survival time and mean onset time of death with or without treatment of anti-IL-6 antibody (Ab) during sepsis." (PMID 21931850, 2011). "WT mice treated with anti-IL-6 antibody showed a similar survival curve to that of plg-/- mice, which suggests that lack of plasminogen improves the chances of survival from sepsis by reducing the production of IL-6." (PMID 21931850, 2011). "Neither interleukin 6 nor C-reactive protein concentrations were significantly different between patients with and without sepsis." (PMID 20929576, 2010). "LBP, IL-6 and CRP levels may serve as good biomarkers for identifying children with severe sepsis and bacteraemia and, thus, may be routinely used in clinical practice." (PMID 20158885, 2010). "In contrast, interleukin 6 and C-reactive protein are markedly higher in postoperative patients, but no further increase is found in patients with severe sepsis." (PMID 20929576, 2010). "High serum levels of IL-6, a crucial immunoregulator in patients with early-phase Gram-negative sepsis, predict poor outcomes for patients with sepsis." (PMID 20939898, 2010). "Although cytokines such as interleukin-6 (IL-6) have been shown to relate to the severity of sepsis and patients outcome, they are not established tools for diagnosis and clinical decision making." (PMID 20230641, 2010). "The levels of the inflammatory cytokine IL6 in our study showed statistically significant differences between infected patients without SIRS and sepsis patients: IL6 was markedly higher in sepsis patients than in patients without SIRS." (PMID 20158885, 2010). "Furthermore, LBP, IL-6 and CRP were significantly higher in children with severe sepsis compared to those ones with less severe sepsis (p < 0.001)." (PMID 20158885, 2010). "While CpG methylation can mediate more sustained suppression of certain genes, the promoters of several of the inflammatory genes suppressed in sepsis, including TNF-α, IL-6, IL-12 p40, and iNOS, contain few CpG motifs and are therefore less susceptible to this form of epigenetic regulation." (PMID 20585389, 2010). "Procalcitonin, interleukin 6, and C-reactive protein concentrations were tested for differences between patients with and without sepsis." (PMID 20929576, 2010). "In our LD50 experiments, IL-6, often reported as the best marker of the severity of infectious (or even non-infectious) stress in humans and to have a prognosis value in sepsis, was not differentially expressed according to the outcome." (PMID 20076757, 2010). "Additionally, treatment with ghrelin in these sepsis models reduced serum concentrations of proinflammatory cytokines like TNF-α and IL-6." (PMID 20500817, 2010). "Not surprisingly, different markers of systemic inflammation (e.g., IL-6) and mediators involved in the redox homeostasis (e.g., TRX1, MIF) are significantly elevated during ongoing sepsis, whereas only IL-6 differed between patients after major abdominal surgery and healthy volunteers." (PMID 20847814, 2010). "Whereas the findings in regard HMGB1 were inconsistent in identification of patients with infections and those without, IL-6 has been suggested to be a suitable early inflammatory marker, with levels correlating well with the severity and prognosis of sepsis." (PMID 20158885, 2010). "A positive correlation was found among leptin, IL-6 and TNF-α in both SIRS and sepsis groups." (PMID 20230641, 2010). "The incidence of Gram-negative bacteria and CRP and IL-6 blood level were significantly higher in the septic shock group than in the sepsis and severe sepsis groups." (PMID 20202204, 2010). "We thus established a human in vivo sepsis model (the human endotoxin model) in order to investigate the effect of glutamine on the response of TNF-α, IL-6, cortisol and white blood cell (WBC) subpopulations to a standardized inflammatory stimulus (intravenous injection of E. coli endotoxin)." (PMID 19173710, 2009).
Sepsis (continued). "In a ROC analysis to distinguish between patients with noninfectious SIRS and patients with sepsis/severe sepsis, IL-6, LBP and CRP had an AUC of 0.87, 0.86 and 0.84, respectively; compared to 0.75 for PCT." (PMID 19578505, 2008). "The NPV (negative predictive value) is 77%, meaning that in 77% of the cases patients with an IL6-value at the first day of fever below the cut-off-level will not develop sepsis or a longer fever period." (PMID 18321393, 2008). "In ourstudy, it was observed that IL-6 levels of newborn with culture-proven sepsisand culture-negative sepsis were significantly higher than controls (P<.05)." (PMID 18274637, 2007). "Oberholzer and coworkers observed that IL-6 concentrations and APACHE II score were correlated, and that the combination of these variables exhibited good performance in predicting mortality in patients with severe sepsis." (PMID 17448250, 2007). "Research to evaluate the production of cytokines like IL-1, IL-6 and TNF-α by activated microglia in septic patients might strengthen the hypothesis of the role of microglia in sepsis and co-existing neurological symptoms." (PMID 17224051, 2007). "Concentrations of IL-1β, IL-6, IL-7, IL-8, IL-10, IL-13, interferon-γ, MCP-1 and tumour necrosis factor-α were significantly higher in septic shock patients than in those with severe sepsis." (PMID 17448250, 2007). "This included traditionally evaluated cytokines (IL-1β, IL-6, IL-8, IL-10 and TNF-α) and a number of cytokines that are not commonly associated with sepsis (IL-7, IL-13, IFN-γ and MCP-1)." (PMID 17448250, 2007). "Therefore, we propose that EGCG rescues mice from lethal sepsis partly through inhibiting systemic HMGB1 accumulation, as well as HMGB1-induced release IL-6 and KC." (PMID 17987129, 2007). "Variation in the IL-10, IL-6 and CD14 genes may be genetic factors influencing the development and outcome of sepsis in the premature newborn." (PMID 16611358, 2006). "No significant trend between haplotype and risk for sepsis was observed, although the highest incidence of late BSI was in infants with the IL-10 -1082AA: IL-6 -174 CC haplotype." (PMID 16611358, 2006). "In a ROC analysis to distinguish between patients with noninfectious SIRS and patients with sepsis/severe sepsis, IL-6, LBP and CRP had an AUC of 0.87 (95% CI 0.78–0.96), 0.86 (95% CI 0.77–0.95) and 0.84 (95% CI 0.75–0.92), respectively." (PMID 16569262, 2006). "It is interesting to note that in their study nicotine treatment did not have a significant effect on IL-6, which appears to be a marker in the prognosis in sepsis in patients and animals." (PMID 16480493, 2006). "Levels of LBP, IL-6 and CRP increased progressively with increasing severity of infection/sepsis." (PMID 16569262, 2006). "IL-6 is widely accepted as a marker for disease severity in septic shock but elevations are not sepsis specific." (PMID 16137344, 2005). "Furthermore, total bile acid, interleukin (IL)-6, and tumor necrosis factor-α concentrations were downregulated after FXR activation, whereas IL-10 concentration was upregulated, indicating the alleviated effect of FXR agonist in sepsis." (PMID 40192065, 2025). "A key distinction may be the absence of profoundly elevated cytokine (mainly IL-6 and interferon-gamma) levels in sepsis, which are distinguishing features of the cytokine storm in CRS, particularly in the appropriate clinical context." (PMID 40277755, 2025). "Considering the importance of VA in both anti-inflammatory and proinflammatory immune functions, VAD may contribute to exaggerated inflammatory responses in sepsis, resulting in elevated infection markers such as C-reactive protein (CRP) and interleukin-6 (IL-6)." (PMID 40843069, 2025). "Biomarkers such as C-reactive protein (CRP), interleukin-6 (IL-6), serum amyloid A (SAA), and procalcitonin (PCT) are widely used for diagnosis and treatment-monitoring of various diseases, ranging from infection and sepsis to cardiovascular and autoimmune diseases." (PMID 41002312, 2025).
Sepsis (continued). "Our results support these findings, as patients with SAE exhibited significantly higher IL-6 levels than the non-SAE group, suggesting that IL-6 may serve as a valuable marker for assessing the severity of neurological impairment in sepsis." (PMID 40635709, 2025). "At 2 h post-LPS stimulation, the Cp1 group presented obviously increased IL-6 levels compared with those of the CLP control group, suggesting that Cp1 exposure beneficially modulated the LPS responsiveness of CLP-treated mice during the intermediate phase (24 h) of sepsis." (PMID 41188260, 2025). "On the one hand, statins executed anti-inflammatory effects by modulating upstream intracellular signaling pathways, on the other hand, cytokines such as TNF, IL-1β, and IL-6, were pivotal in the manifestation of SIRS and might serve as prognostic biomarkers in sepsis." (PMID 39927168, 2025). "In our LPS-induced sepsis model, the CL-treated mice reconstituted with SLC25A33-silenced BMDMs exhibited a higher survival rate and decreased secretion of pro-inflammatory cytokines, such as TNF-α, IL-6, and IL-1β, relative to mice reconstituted with vehicle-treated BMDMs." (PMID 40384854, 2025). "It suppresses the expression of TNF-α, IL-6, and malondialdehyde in serum and tissues, and augments the levels of SOD and GSH to counteract sepsis-related damage induced by abdominal puncture-induced sepsis, thereby preserving intestinal mucosal barrier function." (PMID 40258745, 2025). "Intraperitoneal administration of PEG-pro-DCD-C34S markedly reduced systemic levels of G-CSF, IL-6, keratinocytes-derived chemokine (KC), MCP-1, macrophage inflammatory protein-2 (MIP-2), and soluble tumor necrosis factor receptor I (sTNFRI)—surrogate markers of sepsis." (PMID 40806779, 2025). "Although this was not obvious in our study, circulating IL-6 is considered the most reproducible systemic biomarker of inflammation and prognosis in sepsis, trauma, and severe viral disease, particularly when evaluated longitudinally rather than as a single measurement." (PMID 41463836, 2025). "Similarly, IL-6 is a non-specific pro-inflammatory cytokine that rises in sepsis, autoimmune diseases, and even post-surgical states, independent of brain injury." (PMID 40979014, 2025). "Utilizing data from 238 SIRS and 58 sepsis episodes in a German pediatric intensive care unit (PICU), the researchers identified eight key predictors, including length of PICU stay before onset, interleukin-6 (IL-6), platelet count, procalcitonin, and C-reactive protein (CRP)." (PMID 41357433, 2025). "Additionally, while blood samples were collected within 48 h of admission, variations in sampling timing may have affected biomarker levels, particularly given the dynamic expression patterns of inflammatory mediators such as IL-6 and CRP during early sepsis." (PMID 40714984, 2025). "For example, interleukin (IL)-1, IL-6, IL-12, interferon (IFN)-γ, macrophage migration inhibitory factor (MIF), IL-10, transforming growth factor (TGF)-β, and IL-4 attempt to restore the immunological equilibrium and balance the pro- and anti-inflammatory cascades during sepsis." (PMID 40142568, 2025). "Furthermore, while additional inflammatory markers such as IL-6, procalcitonin, and neutrophil maturation indices would have enriched the dataset, these are not routinely incorporated into neonatal sepsis evaluations in our clinical setting." (PMID 40564685, 2025). "Finally, other validated sepsis-related biomarkers (e.g., procalcitonin and IL-6) were not evaluated, despite the fact that the inflammatory markers employed in this investigation are easily available and generated from standard blood testing." (PMID 40870412, 2025).
Sepsis (continued). "Furthermore, IL-6 levels did not exhibit a significant effect on the development of sepsis in either univariate or multivariate analyses." (PMID 41011807, 2025). "Our results might contribute to the notion that serum IL-6 measurements, maybe already in the emergency department, could help differentiate the patients who could benefit from earlier ICU admittance and hopefully enhance sepsis survival." (PMID 40142279, 2025). "Positive associations with interleukin-6 were observed in males, but not in females, which may be due to the smaller number of women with SIRS/sepsis." (PMID 39997462, 2025). "In the early stage of sepsis, the upregulation of CREB5 may enhance the transcriptional activity of inflammatory factors such as IL-6 and TNF-α by directly binding to the promoter region of inflammatory factors, thus driving the inflammatory response of CD16+ monocytes." (PMID 41246299, 2025). "Anti-inflammatory therapies, such as IL-6 and TNF-α inhibitors, show promise in mitigating inflammation, while immune checkpoint inhibitors like anti-PD-1 and anti-CTLA-4 antibodies are being explored to restore immune function in sepsis and enhance antitumor immunity in cancer." (PMID 40563999, 2025). "In our study, we observed a lower relative expression of miR-146b-5p and higher levels of IL-6 in non-survivors, suggesting that miR-146b-5p may influence sepsis prognosis by modulating inflammatory responses." (PMID 40642098, 2025). "Compared with wild-type mice in CLP sepsis models, mice with FXI knockout had smaller increases in the plasma levels of inflammatory cytokines TNF-α and interleukin-10 (IL-10), delayed responses to the inflammatory cytokines IL-1β and IL-6, and a greater survival advantage." (PMID 38213768, 2024). "Moreover, an observational study assessed the following biomarkers as an indicator of sepsis-survival in sepsis patients admitted to the ICU: procalcitonin (AUC: 0.57), C-reactive protein (AUC: 0.51), interleukin-6 (AUC: 0.69), and monocyte chemotactic protein 1 (AUC: 0.64)." (PMID 38674159, 2024). "Additionally, the blockade of APOH after CLP led to a significant increase in the levels of serum and peritoneal inflammatory cytokines, such as TNF-α, IL-1β, and IL-6, alongside a decrease in IL-10 levels after non-severe sepsis." (PMID 38291524, 2024). "To investigate whether the anti-PD-L1 antibody affected monocyte function, we selected three important cytokines, IL-6, IL-10, and TNF-α, used ELISA to assess cytokine production in the CLP-induced sepsis model and anti-PD-L1 antibody-treated septic mice at 24, 48, and 72 h." (PMID 37776443, 2024). "Since severe sepsis is accompanied by systemic inflammation that results from excessive release of cytokines into the systemic circulation, it has been observed that the serum levels of TNF-α and IL-6 were markedly enhanced 6 h after multiple injections of 5 μg Ec-OMVs in mice." (PMID 39201409, 2024). "At the very early stages of sepsis, IL-6 production by B cells may not augment the inflammatory response to toxin, with delayed onset of its pathogenic role." (PMID 38197178, 2024). "Another study revealed that naringenin protects against sepsis-related lung damage through AMPK-activating transcription factor 3 (ATF3)-dependent negative regulation of the LPS/TLR4 signaling pathway, suppressing the expression of TNF-α, IL-6, TLR4, iNOS, cyclo-oxygenase-2 (COX2), and NOX2." (PMID 39126050, 2024). "Similarly, treatment with Ginsenoside Rb1 or fisetin (a natural flavonoid) mitigates the LPS-induced kidney damages by inhibiting IL-6, TNF-α, COX-2 expression, AKT activation and prevents from sepsis-mediated death in mice by down-regulating the MAPK signaling." (PMID 39267971, 2024).